IGFBP7 (insulin like growth factor binding protein 7)
Diseases named in the same sentence as IGFBP7 in open-access papers (continued):
Sharing a sentence is not in itself a finding about the gene and the disease.
esophageal cancer (6 papers, 2008 to 2024). A primary or metastatic malignant neoplasm involving the esophagus. "Given the association between IGFBP7 and disease, we also compared serum IGFBP7 levels in patients with endometriosis or endometrial, colorectal or esophageal cancer to normal healthy individuals." (PMID 19019211, 2008). "Increased expression of IGF1R, IGFBP3, IGFBP4, IGFBP7, and IGFBP8 was reported in human esophageal cancer, while the expression of IGFBP2 and IGFBP6 was reduced." (PMID 32041673, 2020).
kidney injury (6 papers, 2018 to 2025). Trauma to the kidney. "Our study proves the diagnostic utility of urinary [TIMP-2]·[IGFBP7] in a diverse patient population after a defined initial event of kidney injury and standardized ICU management." (PMID 29751827, 2018). "Increased urinary IGFBP-7 levels have been repeatedly reported following renal injury of various etiologies, to such an extent that urinary IGFBP-7 is considered a valid biomarker of kidney injury." (PMID 40524147, 2025). "IGFBP7 is an acknowledged predictive biomarker of acute kidney injury that demonstrates increased levels with conditions of hypoxia and atherosclerotic renal artery stenosis due to decreased renal blood flow." (PMID 34646401, 2021). "IGFBP7 is emerging as a potential therapeutic target for tumors and as one of the detrimental factors that exacerbate acute inflammatory injury, such as acute kidney injury and acute lung injury." (PMID 38840498, 2024). "In this context, a unique [TIMP-2]∙[IGFBP7] measurement may not able to mirror the complex dynamic of kidney injury, because this accuracy might progressively decrease over time." (PMID 31712687, 2019).
Alzheimer disease (5 papers, 2017 to 2025). A progressive, neurodegenerative disease characterized by loss of function and death of nerve cells in several areas of the brain leading to loss of cognitive function such as memory and language. "Although this exact pathway did not emerge from our analyses, we did find associations for SPON1 and IGFBP7 and similar Alzheimer’s disease-related pathways in protein glycosylation and ether lipid metabolism, confirming the relevance of these pathways." (PMID 41280530, 2025). "Nonetheless, IGFBP-7 could be a promising biomarker in the context of depression, since IGFBP-7 has been proposed as a potential therapeutic target in Alzheimer’s disease, for which depression is a risk factor." (PMID 37894932, 2023). "Researchers from our group have previously studied the roles of both IGF-2 and IGFBP-7 in schizophrenia, as well as in the extinction of fear memories in mouse models and as possible targets for treatment in Alzheimer’s disease." (PMID 37894932, 2023). "Members of our group have previously investigated the role of IGF-2 and IGFBP-7 in the extinction of fear memories and as a potential drug target in Alzheimer’s disease (AD)." (PMID 36076984, 2022). "Interestingly, brain tissue and blood serum isolated from Alzheimer’s disease patients demonstrated IGFBP7 upregulation." (PMID 28134287, 2017).
atherosclerosis (5 papers, 2020 to 2023). A disease characterized by the build-up of fatty material and calcium deposition in the arterial wall resulting in partial or complete occlusion of the arterial lumen. "Our analysis demonstrates that the editing of IGFBP7 is markedly increased with cardiac or vascular injury (increases in LV editing from 16% to 26% and 26% to 34% in ischemic cardiomyopathy and atherosclerosis, respectively)." (PMID 37036839, 2023). "We observed an increase in both intronic and recoding editing in atherosclerosis patients, with a particular increase in Insulin-like growth factor binding protein 7 (IGFBP7) gene editing." (PMID 37036839, 2023). "Proteins related to atherosclerosis/cardiovascular risk (e.g., SELE/E-selectin, IGFBP7, CHIT1/ chitotriosidase-1, AXL) also significantly decreased after treatment." (PMID 32849633, 2020). "Further research on the accurate dependence of IGFBP-7 and atherosclerosis should be conducted." (PMID 35625639, 2022). "Further research on the role of IGFBP-7 in atherosclerosis and PAD development is required." (PMID 35625639, 2022). "IGFBP7′s role in atherosclerosis development is yet to be determined." (PMID 35204773, 2022). "Our research, which is as far as we know the first one about the importance of IGFBP-7 in PAD development, seems to confirm the possible role of this protein in peripheral arteries atherosclerosis." (PMID 35625639, 2022). "The results obtained from our current study, indicating significantly higher levels of IGFBP7 in the group of patients with IHD compared to the population group, confirm the possible role of this protein in atherosclerosis development." (PMID 35204773, 2022). "In this list, two novel biomarker candidates, NPC2 and IGFBP7, were identified along with several proteins, such as THBS1, that have been reported to be involved in atherosclerosis or AA." (PMID 32286426, 2020).
cardiac arrest (5 papers, 2018 to 2025). Cessation of breathing and/or cardiac function. "The performance of [TIMP-2]·[IGFBP7] was prospectively analysed in 48 patients with shock following out-of-hospital cardiac arrest (OHCA)." (PMID 29751827, 2018). "The study aimed to see if measuring urine [TIMP-2] × [IGFBP-7] levels immediately after cardiac arrest might reliably predict the onset of severe AKI (KDIGO stage 3) within 48 h of ICU admission." (PMID 39001241, 2024). "Several studies have reported that urinary [TIMP-2] × [IGFBP-7] predicts the development of AKI after major surgery, emergency department admission, out-of-hospital cardiac arrest, and in critically ill patients." (PMID 31315590, 2019).
Cirrhosis (5 papers, 2009 to 2025). A chronic disorder of the liver in which liver tissue becomes scarred and is partially replaced by regenerative nodules and fibrotic tissue resulting in loss of liver function. "The association of IGFBP2 and IGFBP7 with cirrhosis and NAFL is consistent with previous studies of NASH progression." (PMID 36280732, 2022). "In previous studies, IGFBP-7 was found to be increased preoperatively in LT patients compared to healthy individuals, a finding which may be explained by the liver steatosis, fibrosis, or cirrhosis present in most of the patients." (PMID 40524147, 2025).
diabetic nephropathy (5 papers, 2016 to 2024). "IGFBP7 has been implicated in diabetic nephropathy, with elevated levels observed in the urine of affected patients." (PMID 38255264, 2024). "Meanwhile, while plasma IGFBP7 concentrations can be used to predict renal and cardiac events in participants with T2DM and high cardiovascular risk, more research is needed on the association between circulating IGFBP7 and the progression of diabetic nephropathy." (PMID 36293317, 2022). "To confirm the localization of IGFBP7 in renal tubular cells, we conducted an immunohistochemical analysis using tissue samples from human kidney in renal biopsies from patients with overt diabetic nephropathy." (PMID 26974954, 2016).
esophageal adenocarcinoma (5 papers, 2019 to 2023). A malignant tumor with glandular differentiation arising predominantly from Barrett mucosa in the lower third of the esophagus. "DNA methylation of the IGFBP7 promoter resulted in an association with transcriptional silencing in esophageal adenocarcinoma and Barrett carcinoma cell lines." (PMID 32500027, 2020). "In addition, in esophageal adenocarcinoma, patients with DNA methylation in the IGFBP7 promoter region often exhibit better survival rates." (PMID 37568781, 2023). "Furthermore, IGFBP7 promoter methylation level upregulation was common in Barrett’s oesophagus and oesophageal adenocarcinoma and was related to IGFBP7 knockdown." (PMID 37660019, 2023). "Interestingly, GC patients with positive H. pylori infection (Hp) or with negative Barrett’s esophagus tended to possess relatively high expression of IGFBP7." (PMID 36681667, 2023).
Hypertension (5 papers, 2019 to 2025). The presence of chronic increased pressure in the systemic arterial system. "Risk factors for AKI development were male sex, history of hypertension, low albumin levels, and high [TIMP-2]⋅[IGFBP7] and NGAL levels." (PMID 39982587, 2025). "GDF-15 (p < 0.001), Troponin-T (p = 0.002), FGF-23 (p = 0.006), and IGFBP-7 (p = 0.018) abundance was higher in patients with hypertension." (PMID 35859587, 2022).
pancreatic cancer (5 papers, 2014 to 2023). "Methylation-dependent silencing of IGFBP7 was associated with unfavorable outcomes in colorectal, breast, and pancreatic cancers." (PMID 30609749, 2019). "IGFBP7 is a secreted protein which is known to be a tumor suppressor in breast, brain, colon, lung, liver and pancreatic cancers." (PMID 24427302, 2014). "By IHC, they found that IGFBP7 expression was downregulated in pancreatic cancer tissue compared to adjacent nontumour tissue." (PMID 37660019, 2023).
atrial fibrillation (4 papers, 2021 to 2026). A disorder characterized by an electrocardiographic finding of a supraventricular arrhythmia characterized by the replacement of consistent P waves by rapid oscillations or fibrillatory waves that vary in size, shape and timing and are accompanied by an irregular ventricular response. "Atrial fibrillation, enlarged LAA and E/e’ > 8 were also associated with higher concentrations of IGFBP7." (PMID 34217226, 2021). "Experimental evidence supports the role of cellular senescence in the pathophysiology of atrial fibrillation (AF) and suggests that Insulin-like Growth Factor Binding Protein-7 (IGFBP7) is an important senescence-inducing factor." (PMID 40814448, 2025). "For the observed associations for NPPB, ITIH3, and IGFBP7 with multiple outcomes and for the association of SVEP1 with atrial fibrillation, our findings were negative for colocalization, suggesting two different causal variants for protein level and outcome." (PMID 38225249, 2024).
colorectal tumors (4 papers, 2009 to 2023). "In this study, we found that IGFBP7 DNA hypermethylation is tumor-specific and tightly associated with colorectal tumors carrying BRAFV600E and exhibiting CIMP." (PMID 20027224, 2009). "Previous studies observed CIMP-high and BRAF mutations in an early-stage colorectal neoplasm, and acquisition of BRAF mutation was considered to be mediated by DNA hypermethylation of several genes, including IGFBP7 and BMP3." (PMID 28623901, 2017). "We identified the IGFBP7 promoter CpG island as a target for DNA methylation in colorectal tumors harboring BRAFV600E (P value = 3.1×10−9, Odds ratio = 12)." (PMID 20027224, 2009).
depression (4 papers, 2019 to 2023). "Therefore, we calculated different linear regression models using the backpropagation methodology to predict the effects of group (control, depression), age (years) and gender (male, female) over the IGF-2 and IGFBP-7 levels." (PMID 37894932, 2023). "Curiously, as far as we have found, no study has yet evaluated either IGF-2 or IGFBP-7 circulating levels in patients diagnosed with bipolar disorder or depression." (PMID 36076984, 2022). "In the present study, the levels of IGFBP-7 were initially found to be significantly increased in depressed patients, but after correcting for age and gender, we found that depression might not explain this difference." (PMID 37894932, 2023).
fibrosis (4 papers, 2024 to 2025). the formation of excess fibrous connective tissue in an organ or tissue in a reparative or reactive process. "Studies have demonstrated a correlation between increased IGFBP7 levels and the severity of steatosis and fibrosis in patients with NAFLD." (PMID 38709454, 2024). "Serum levels of IGFBP-7 were significantly increased in the subjects with fibrosis (F1C and F2), but its hepatic expression was only increased in the F2 livers." (PMID 38541155, 2024). "When analyzed according to the fibrosis stages, F2 exhibited a higher percentage of senescent cells compared with F0 and F1C, suggesting that IGFBP-7 and its induced senescence might have a role in the progression from mild-to-moderate fibrosis during NAFLD." (PMID 38541155, 2024). "Conversely, a decrease in IGFBP7 has been shown to slow the progression of NAFLD and prevent fibrosis." (PMID 38709454, 2024). "Both IGFBP-7 and cellular senescence were significantly higher during NAFLD and fibrosis in MCD-fed mice." (PMID 38541155, 2024). "Several factors determine which subjects develop fibrosis during NAFLD: the well-documented oxidative stress, endoplasmic reticulum stress, and, as suggested by our findings, IGFBP-7 and its resulting cellular senescence." (PMID 38541155, 2024). "The observation of IGFBP-7 increased in serum in both borderline and definite NASH stages as well as during the F1C and F2 fibrosis stages, combined with its identification as a predictor by both crude and adjusted lipid models, suggests a possible role for this protein in the progression of NAFLD." (PMID 38541155, 2024).
head and neck squamous cell carcinoma (4 papers, 2015 to 2023). A squamous cell carcinoma that arises from any of the following anatomic sites: lip and oral cavity, nasal cavity, paranasal sinuses, pharynx, larynx, and salivary glands. "Additionally, IGFBP-7 is implicated in the biology of a range of tumours including lung squamous cell carcinoma and head and neck squamous cell carcinoma." (PMID 26407999, 2015). "This study investigates the causes and underlying mechanisms of aberrant IGFBP-7 expression in unravelling head and neck squamous cell carcinoma (HNSCC)." (PMID 25880247, 2015).
keloid (4 papers, 2010 to 2024). An irregularly shaped, elevated mark on the skin caused by deposits of excessive amounts of collagen during wound healing. "Analysis of the keloid fibroblast transcriptome and protein levels upon IGFBP7 treatment revealed decreased levels of TGF-β1, Col I, VEGF, and pro-inflammatory markers interleukin-6 (IL-6) and interleukin-8 (IL-8), while levels of TGF-β3 were increased." (PMID 39045455, 2024). "During dysregulated skin wound healing, such as keloid formation, IGFBP7 has been described to have inhibitory effects." (PMID 39045455, 2024). "Moreover, the authors concluded that IGFBP-7 secreting ASCs inhibited keloid formation via the BRAF/MAPK/ERK signaling pathway." (PMID 39045455, 2024). "Similarly, co-culture of ASCs, known to express IGFBP7, inhibited keloid fibroblast proliferation, while their migration or apoptosis was unaffected." (PMID 39045455, 2024). "Congruently, ASCs were able to inhibit collagen I production in keloid fibroblasts, while there was no change when co-cultured with IGFBP7-silenced ASCs." (PMID 39045455, 2024). "However, the results of the present study revealed for the first time the downregulation of five genes (ANXA1, ASPN, IGFBP7, LGALS1, and PTN) which is in contrast to the upregulation of the same genes in African and Caucasian keloid samples." (PMID 32085797, 2020). "A statistically significant (P < .05) differential expression and a fold change of more than 2 were determined between keloid margin and internal control biopsy samples for 10 genes, including ACAN, ASPN, C5orf13, HIF1A, IGFBP7, INHBA, LGALS1, PTN, SERPINH1, and TNFAIP6." (PMID 20418938, 2010).
lymph node metastasis (4 papers, 2021 to 2023). "They reported that IGFBP7 expression upregulation was positively correlated with poor disease-specific survival, depth of invasion, lymph node metastasis, distant metastasis, recurrence, and pathological stage." (PMID 37660019, 2023). "Low IGFBP7 expression is related to a poor prognosis, including the depth of invasion, lymph node metastasis, and TNM stage." (PMID 37660019, 2023). "Elevated pre‐operative CEA, larger CRLM, a greater number of CRLM, post‐operative complications, presence of primary lymph node metastases, IGFBP7 stroma positivity and POSTN stroma positivity were all independent predictors of poorer DFS." (PMID 34874125, 2022). "In addition, IGFBP7 expression at the mRNA level was higher in advanced stages, in tumours with lymph node metastasis, and in those with distant metastasis and recurrence." (PMID 37660019, 2023).
Myocardial fibrosis (4 papers, 2021 to 2025). "In the cardiovascular system, IGFBP-7 has been linked to myocardial fibrosis, endothelial dysfunction, and PAH." (PMID 41169887, 2025). "IGFBP7 has been defined as a biomarker of myocardial fibrosis and was shown to be upregulated by TGF-β25." (PMID 37009790, 2023). "The interaction between IGFBP7 and KNG2 was associated with the biological processes of the extracellular space and the severity of myocardial fibrosis in patients with HFpEF." (PMID 34306013, 2021).
steatosis (4 papers, 2017 to 2025). Increased lipid within the cytoplasm of cells. "Circulating levels of IGFBP7 have been strongly associated with hepatic IGFBP7 expression as well as with steatosis and fibrosis stage in patients with NAFLD." (PMID 38709454, 2024). "Analyses of these proteins showed a negative correlation between IGFBP2, IGFBP4, and steatosis grade (r = −0.49, p < 0.02; r = −0.12, p < 0.02), while IGFBP6 and IGFBP7 were positively associated with steatosis (r = 0.25, p < 0.005; r = 0.35, p < 0.0001)." (PMID 36831184, 2023).
acute lymphoblastic leukemia (3 papers, 2015 to 2024). Leukemia with an acute onset, characterized by the presence of lymphoblasts in the bone marrow and the peripheral blood. "In acute lymphoblastic leukemia (ALL) IGFBP7 expression was associated with adverse outcome and shown to interfere with leukemia cell proliferation." (PMID 25887188, 2015).
adenoma (3 papers, 2014 to 2020). A neoplasm arising from the epithelium. "A strong staining for pSMAD3 and IGFBP7 could be observed in adenomas compared to benign mucosa (Figs EV3A–D and 5A)." (PMID 31793740, 2020). "In fact, in addition to the BRAF-mediated alteration of the MAPK pathway, the inactivating hypermethylation of p16 and IGFBP7 drives the progression of MVHP lesions toward sessile serrated adenomas/polyps, rendering the distinction between MVHP and SSA/P difficult to assess by endoscopy." (PMID 31330830, 2019).
cervical cancer (3 papers, 2010 to 2023). A primary or metastatic malignant neoplasm involving the cervix. "IGFBP7 has been implicated in cervical cancer, and it may influence the persistence of HR-HPV infection." (PMID 28216603, 2017). "IGFBP7 is part of the insulin-like growth factor (IGF) axis, which has been implicated in cervical cancer before." (PMID 20579385, 2010). "Further functional studies are needed to investigate whether the tumour suppressive function of hsa-miR-124 in cervical cancer may in part be mediated via IGFBP7." (PMID 20579385, 2010).
cholangiocarcinoma (3 papers, 2020 to 2023). A carcinoma that arises from the intrahepatic biliary tree (intrahepatic cholangiocarcinoma) or from the junction, or adjacent to the junction, of the right and left hepatic ducts (hilar cholangiocarcinoma). "Higher expression of the IGFBP7 gene in cholangiocarcinoma was associated with better OS." (PMID 33473258, 2020).
congenital heart disease (3 papers, 2014 to 2025). A heart disease that is present at birth. "The same may be true for the missing difference in the baseline [TIMP-2]•[IGFBP7] levels in patients with either immature kidneys (<2 years) or venous congestion resulting from congenital heart disease." (PMID 25343505, 2014). "Urinary [TIMP-2]•[IGFBP7] represent sensitive, specific, and highly predictive early biomarkers for AKI after surgery for congenital heart disease." (PMID 25343505, 2014).